INS (insulin)
Diseases named in the same sentence as INS in open-access papers (continued):
Sharing a sentence is not in itself a finding about the gene and the disease.
Insulin resistance (continued). "Treatment of these animals with HGSD attenuated insulin-resistance and improved insulin signalling." (PMID 32792855, 2020). "Thus, it is not surprising that a dietary pattern characterized by high sugar intake, and therefore continuous stimulation of pancreatic insulin secretion, can, over time, lead to increased insulin resistance and hyperinsulinemia." (PMID 32098332, 2020). "These proinflammatory mediators can directly or indirectly affect inflammation-related pathways, such as the JNK and IKKβ/NF-κB pathways, and also disrupt insulin signaling, eventually leading to systemic insulin resistance and the subsequent development of T2DM." (PMID 33329397, 2020). "Interestingly, overall amelioration of insulin resistance at the level of insulin signaling cascade was more pronounced than the improvement in muscular glucose uptake." (PMID 33036203, 2020). "Participants were divided into two groups based on the relationship between FPG and 2‐hPG (OGTT‐A1/Postprandial‐B1:FPG > 2‐hPG;OGTT‐A2/Postprandial‐B2:FPG ≤ 2‐hPG).Insulin sensitivity was evaluated by Matsuda index and homeostasis model assessment of insulin resistance (HOMA‐IR)." (PMID 32484250, 2020). "Under conditions of insulin resistance 9, target organs tend to be insensitive to insulin, leading to increased levels of blood glucose, which makes β cells constantly secrete insulin and C-peptide, and triggering the rise of plasma insulin and C-peptide levels." (PMID 32913460, 2020). "Significantly increased glycemia after an overnight fasting period of 12 h, especially in the experimental groups on HFD, clearly supports the existence of hepatic insulin resistance and a failure of insulin to suppress hepatic glucose production overnight, which is in line with our results." (PMID 32117058, 2020). "During insulin-treated T1DM, hypoglycemia may promote neuronal destruction whereas insulin resistance during T2DM may decrease the insulin upregulation of GLUT4/Glut4 in hippocampal neuronal membranes." (PMID 32789766, 2020). "In contrast, the casein-fed groups showed a significantly higher hepatic FMO-3 abundance, and the addition of fat in the diet further increased FMO-3, % body fat, and high insulin levels, which have been associated with increased production of TMAO, obesity and insulin resistance." (PMID 32340138, 2020). "In addition, dietary supplementation with WR significantly increased the clearance of a glucose bolus during the OGTT and improved HFD-induced insulin resistance Thus, WR enhanced the glucose–insulin homeostasis by attenuating HFD-induced MAFLD." (PMID 32751062, 2020). "A previous report demonstrated that plasma SAM concentrations were related to higher fasting insulin levels, the homeostasis model assessment of insulin resistance, and the tumor necrosis factor α in a cross-sectional study that involved subjects with metabolic syndrome." (PMID 32850834, 2020). "Moreover, the risk genotype was correlated with a higher value of insulin, HOMA-IR, TyG-index and higher ratio of Triglycerides/HDL-c and Waist*TyG-index, all of them related to insulin resistance." (PMID 32365683, 2020). "PKR can be activated by ERS, which not only directly inhibits tyrosine phosphorylation of IRS-1ser307 and causes insulin resistance but also reduces the phosphorylation of Akt by activating JNK and inhibits insulin signal transduction, indirectly leading to insulin resistance." (PMID 32774144, 2020). "Furthermore, administration of insulin to rats to mimic hyperinsulinemia resulted in insulin resistance." (PMID 32230718, 2020). "Moreover, islets isolated from db/db mice, if removed from their in vivo milieu (hyperglycemia and insulin resistance) and cultured in euglycemia, rapidly recovered glucose‐stimulated insulin secretion capacity." (PMID 33312555, 2020).
Insulin resistance (continued). "Therefore, the beneficial actions of vitamin D include diminished insulin resistance which is observed as an improvement of glucose and lipid metabolism in insulin-sensitive tissues." (PMID 32932777, 2020). "This provides evidence for the importance of predisposition for T2DM in obese individuals that may mediate both insulin resistance and impaired insulin secretion dependent on CD36." (PMID 32796572, 2020). "Interestingly SCD-1 is associated with insulin resistance and adiposity, and mouse experiments have shown that disrupting SCD-1 function can potentially reduce body adiposity and improve insulin sensitivity." (PMID 33173055, 2020). "Elevated androgens in females may promote insulin resistance, highlighting the reciprocal relationship between insulin and androgens." (PMID 33113794, 2020). "We found a gene or genes for hyperglycemia and impaired insulin secretion in the middle segment, one for decreased adiposity in the distal segment, and an interaction of multiple latent genes for obesity, adiposity, and insulin resistance." (PMID 32703163, 2020). "The HL group showed an increase in serum insulin levels and insulin resistance." (PMID 32881885, 2020). "Specifically, mice fed an MCD diet show weight loss, decreased fasted glucose, no insulin resistance and low insulin and leptin levels." (PMID 33324348, 2020). "In the case of JNK deficiency, specific muscles prevent high-fat diet- (HFD-) induced muscle insulin resistance, while cell-permeable JNK inhibitory peptide administration improves glucose tolerance and causes increased insulin sensitivity as seen in obese db/db C57BLKS/J diabetes mice." (PMID 33299532, 2020). "Based on this hypothesis, we performed a subgroup analysis of insulin-resistant women, who displayed an improvement of both hepatic insulin resistance and fasting insulin levels one month after Dmab administration." (PMID 33204260, 2020). "Patients with CGL have severe insulin resistance, which may provide the context for the development of hypertrophic cardiomyopathy, given the effect of insulin on growth." (PMID 32079542, 2020). "Moreover, the mTOR-C1 inactivation enhances the action of phosphatidyl-inositol-3-kinase (PI3K) enzyme which promotes the insulin signaling and decreases the insulin resistance and its sequelae." (PMID 32548072, 2020). "Moreover, metabolic disruptions in obesity can result in increased levels of cortisol, leptin, and insulin, leading to dysregulation of neuroendocrine networks and insulin resistance." (PMID 32102680, 2020). "For example, elevated OxS could have induced insulin resistance by impairing insulin signaling and decreasing Glut4 transcription as reported in other studies, and reductions in OxS in our study could have improved insulin resistance." (PMID 33007928, 2020). "According to the findings of recent studies, treatment with SGLT2 inhibitors plus insulin is a suitable regimen for patients with T2D, especially those requiring a high insulin dose daily and those with insulin resistance, obesity, or high risks of cardiovascular disease." (PMID 32351447, 2020). "As patients with hormone-abnormal PA usually develop insulin resistance and glucose abnormalities, activated insulin signaling in NFPAs might antagonize metabolic disorders, thus preventing excessive hormone secretion." (PMID 33472173, 2020). "Moreover, since adiponectin also acts as an insulin-sensitizing hormone in muscles and the liver, lower levels of adiponectin further contribute to peripheral insulin resistance in obesity." (PMID 31935815, 2020). "3T3-L1 have widely been used to model in vitro insulin-induced insulin resistance." (PMID 32718202, 2020). "Coinciding with our results, it was found that DHEA increases androgen production which in turn may promote insulin resistance through elevated FBG, HbA1c, and fasting plasma insulin levels associated with increased HOMA‐IR index compared to the control group." (PMID 32994975, 2020).
Insulin resistance (continued). "In mouse β-cell lines, this lncRNA species enhanced insulin production and secretion, and it may play a role in the compensatory insulin secretion that occurs in vivo in response to peripheral insulin resistance." (PMID 32595604, 2020). "In the same trial, insulin resistance may have improved as a result of increased adiponectin, an important mediator of the insulin signaling pathway." (PMID 33081175, 2020). "Interestingly, in hepatic insulin resistance, the inhibition of glucose production by insulin is impaired but insulin-induced lipogenesis is unaffected." (PMID 32455838, 2020). "EMS is defined by the presence of insulin dysregulation, characterised by clinical features including hyperinsulinaemia (either at baseline or in response to glucose challenge), hyperglycaemia, and/or evidence of peripheral insulin resistance." (PMID 33233816, 2020). "Moreover, luteolin enhanced blood glucose, hemoglobin A1c, insulin, and homeostasis model assessment of insulin resistance levels." (PMID 32664218, 2020). "Therefore, mimicking OSA in mice by exposing animals to 6 weeks of CIH induces systemic insulin resistance and insulin signaling alterations in epididymal WAT." (PMID 33324235, 2020). "Considering the results of these studies, both impaired insulin secretion and increased insulin resistance could induce glucose intolerance in patients with phaeochromocytoma." (PMID 33324347, 2020). "Insulin resistance, defined as a relative impairment in the ability of insulin to exert its effects on glucose, protein, and lipid metabolism in target tissues, has many detrimental effects on metabolism and is strongly correlated with the deposition of lipids in non‐adipose tissues." (PMID 33191653, 2020). "Additionally, GML-treated HFD-fed mice showed improved fasting glycemia and fasting insulin (P = 0.012 and P < 0.001, respectively), resulting in a remarkable reduction in the homeostasis model assessment of insulin resistance (HOMA-IR) index (P < 0.001)." (PMID 32265324, 2020). "An excess of androgens in PCOS leads to the development of metabolic complications related to this syndrome, including global adiposity, adipocyte hypertrophy and adipocyte dysfunction (e.g., impaired insulin sensitivity), eventually leading to the observed central obesity and insulin resistance." (PMID 32992734, 2020). "It has been reported that certain miRNAs may regulate insulin secretion and play a key role in regulating insulin resistance." (PMID 33511114, 2020). "The hyperglycemia seen following Kindlin-2 loss is driven by impairments in GSIS, insulin expression, and β-cell mass, but not by impacting peripheral insulin resistance." (PMID 31980627, 2020). "Insulin resistance with impaired glucose metabolism induced by a high-fat diet appears faster in adipose tissue and the liver than in muscles in which the deterioration of insulin action requires more time." (PMID 32796572, 2020). "However, since insulin resistance also produces relative hypersecretion and thus hyperinsulinemia, distinguishing the direct influence of insulin resistance on insulin clearance from that mediated by the saturative effects of hyperinsulinemia is challenging." (PMID 33324238, 2020). "Such a measure cannot be used to test the hypothesis that insulin resistance leads to the failure of insulin to regulate glucose." (PMID 33365205, 2020). "Monocyte chemoattractant protein 1 (MCP-1), the cytokine that considered interferes with the action of insulin and promotes insulin resistance and glucose intolerance, was also elevated in the liver and adipose tissue of the HFD mice but reduced in the LLE + HFD mice." (PMID 32639947, 2020). "An excess of androgens in women with polycystic ovary syndrome (PCOS) disrupts hepatic glucose metabolism as a result of a reduced glucose concentration in blood due to insulin action and glycogen synthesis; furthermore, PCOS predisposes women to insulin resistance (IR)." (PMID 32290381, 2020).
Insulin resistance (continued). "A two-way relationship between insulin and bone has been suggested by preclinical studies, showing a vicious cycle in which bone influences insulin sensitivity, and may be in turn affected by insulin resistance." (PMID 33537005, 2020). "Db/db mice are the models with impaired insulin secretion and insulin resistance." (PMID 32097444, 2020). "In addition to requiring more insulin for glucose homeostasis, insulin resistance affects endothelial function." (PMID 31871214, 2020). "According to the studies, resveratrol and barberry might reduce insulin resistance by regulating insulin signaling pathway through increasing protein kinase B (PKB) expression." (PMID 32923930, 2020). "Insulin signaling was assessed in the hippocampus in order to evaluate whether IF could ameliorate brain insulin resistance." (PMID 32071312, 2020). "While inhibiting SCD1 function may also result in the accumulation of fatty acid metabolites that are deleterious to insulin signaling, and accordingly, the development of fatty acid-induced insulin resistance." (PMID 32973516, 2020). "In conclusion, the present study demonstrates that EMP could increase insulin sensitivity, improve insulin resistance, alleviate hepatic steatosis and ameliorate glucose intolerance in T2D rats." (PMID 32256445, 2020). "Both elevated flux through the hexosamine biosynthetic pathway and increased O-GlcNAc modification of insulin signaling proteins were found to be associated with insulin resistance and impaired GLUT4 translocation in response to insulin in muscle and fat tissue." (PMID 32591906, 2020). "EPA and DHA containing Ω-3 PUFAs have anti-obesity, anti-insulin resistance and anti-inflammatory functions by enhance insulin sensitivity due to declining inflammatory cytokines including tumor necrosis factor, interlukin-6 and enhancing emission of anti-inflammatory adiponectin." (PMID 32928224, 2020). "Studies are also needed to understand if treatments with insulin-sensitizing agents, such as metformin, could determine a different response in insulin resistance based upon Hp phenotypes." (PMID 32695161, 2020). "Current findings imply that propofol may turn into insulin-sensitizing molecules during situations of existing insulin resistance, which involve FGF-21, GLP-1, and ER stress." (PMID 32679813, 2020). "Type 2 diabetes primarily occurs because of defects in insulin secretion and insulin resistance." (PMID 33551987, 2020). "Moreover, it has been shown that the neutrophil-secreted enzyme NE impairs insulin signaling and increases insulin resistance." (PMID 32377527, 2020). "In the current study, we questioned whether hyperinsulinemia-driven excessive insulin signaling in peripheral tissue contributes to the development of diet-mediated insulin resistance, and/or NAFLD." (PMID 32350271, 2020). "Therefore, another question is if the insulin action on PT glucose transport is impaired in insulin resistance." (PMID 32377524, 2020). "Whereas the IR-Akt transduction pathway may account for insulin resistance in the glycemic context of T2D, other disease aspects of T2D surprisingly present full response to insulin, implying “selective insulin resistance”." (PMID 32128655, 2020). "Pearson’s correlation analysis showed that the decreased ALFF value in the left middle frontal gyrus (MFG.L), which is related to poor executive performance and depressive disorders, was negatively correlated with the plasma insulin level in subjects with insulin resistance." (PMID 33362718, 2020). "Therefore, inflammation impairs insulin signaling by activating inflammation-related factors as well as the IKKβ/NF-κB and JNK pathways, thereby increasing the risk of insulin resistance in aging skeletal muscle." (PMID 32082422, 2020). "Similarly, brain insulin resistance can be defined as the failure of brain cells to respond to insulin and its corresponding IRs." (PMID 32365816, 2020).
Insulin resistance (continued). "To determine whether BAT METTL3 regulates systemic glucose homeostasis and insulin resistance, we performed glucose tolerance tests and insulin tolerance tests on mice fed with HFD for 8 weeks (16 weeks old)." (PMID 32245957, 2020). "Here, we demonstrate that in humans, FAM13A alleles are associated with increased FAM13A expression in subcutaneous adipose tissue (SAT) and an insulin resistance-related phenotype (e.g. higher waist-to-hip ratio and fasting insulin levels, but lower body fat)." (PMID 32193374, 2020). "Similarly, to hepatocytes and myocytes, the development of insulin resistance in adipocytes is related to impaired insulin signaling." (PMID 32932777, 2020). "Disruption of adiponectin leads to high-fat diet–induced insulin resistance and levels are low in humans with obesity and insulin resistance while adiponectin levels are increased by insulin-sensitizing peroxisome proliferator-activated receptors (PPAR)γ agonists." (PMID 31963572, 2020). "Thus, glucose homeostasis observed in this model is marked by the robust plasticity of β-cells (compensatory increase of insulin secretion) in the face of progressive insulin resistance occurring during 18 weeks of HSD consumption." (PMID 32187264, 2020). "Similarly, genetic deletion or pharmacological inhibition of CypD interrupts MAM integrity and induces hepatic insulin resistance in mice, while CypD overexpression in mice primary hepatocytes increases mitochondria-ER contacts and improves insulin action." (PMID 33195204, 2020). "As might be expected from their function in insulin pathways, the Tm7sf2–/– animals exhibited a mild insulin resistance phenotype." (PMID 33330474, 2020). "The major characteristics of this disease includes insulin resistance in the liver, skeletal muscle, adipose tissue, and brain, and the failure of the pancreatic β-cell to compensate for insulin resistance by increasing insulin secretion." (PMID 33277568, 2020). "Indeed, insulin resistance alters this role in cognition regulation, while low GI improves the insulin sensitivity and should thus improve cognition." (PMID 33003562, 2020). "Since our previous work showed the importance of hepatic glutathione and nitric oxide on proper insulin action, it is hypothesized that an intraportal vein administration of both would be sufficient to overcome dietary sucrose induced-insulin resistance." (PMID 32942712, 2020). "We did not have measurements of insulin beyond baseline assessment, which impedes us from evaluating the evolution of insulin resistance and its association with DRI." (PMID 32867285, 2020). "This chronic inflammatory state might contribute to the development of T2D by increasing insulin resistance in peripheral tissues (mainly in the liver, muscles, and adipose tissue) and by targeting pancreatic islets and in this way impairing insulin secretion." (PMID 32397353, 2020). "Inverse associations were seen between a sphingomyelin composite score and C-reactive protein, a dihydroceramide composite score and diastolic blood pressure, and the final principal component that included glutathionone with fasting insulin and the homeostatic model of insulin resistance." (PMID 33079935, 2020). "Furthermore, EGb761 oral supplementation of HFD-fed mice can dose-dependently enhance glucose tolerance, decrease insulin levels, and diminish parameters of insulin resistance." (PMID 32317975, 2020). "However, the study suggesting a role for insulin is controversial, since high GI induces insulin resistance, while low GI improves insulin sensitivity." (PMID 33003562, 2020). "In addition, insulin resistance is an adaptation to the very high glucose requirements for lactation, thereby conserving glucose for lactation by limiting its use by insulin-sensitive tissues (muscle, adipose tissue etc.)." (PMID 32872233, 2020).